TFAP2B (transcription factor AP-2 beta)
Description:
Sequence-specific DNA-binding protein that interacts with inducible viral and cellular enhancer elements to regulate transcription of selected genes. AP-2 factors bind to the consensus sequence 5'-GCCNNNGGC-3' and activate genes involved in a large spectrum of important biological functions including proper eye, face, body wall, limb and neural tube development. They also suppress a number of genes including MCAM/MUC18, C/EBP alpha and MYC. AP-2-beta appears to be required for normal face and limb development and for proper terminal differentiation and function of renal tubular epithelia.
Synonyms: AP2-B; AP-2beta; AP-2B; PDA2
Tractability: PROTAC: UniProt records ubiquitination sites on it; ubiquitination databases record sites on it.
Gene: Protein-coding gene on chromosome 6 (50,818,723 to 50,847,619, forward strand). Ensembl gene ENSG00000008196.
Subcellular location: Nucleus
Subcellular location (Human Protein Atlas): Nucleoplasm
Pathways (Reactome):
Gene expression (Transcription): Activation of the TFAP2 (AP-2) family of transcription factors; Negative regulation of activity of TFAP2 (AP-2) family transcription factors; TFAP2 (AP-2) family regulates transcription of growth factors and their receptors
Developmental Biology: Specification of the neural plate border
Metabolism of proteins: SUMOylation of transcription factors
Gene Ontology:
Molecular function: cis-regulatory region sequence-specific DNA binding; DNA-binding transcription activator activity, RNA polymerase II-specific; DNA-binding transcription factor activity; DNA-binding transcription factor activity, RNA polymerase II-specific; protein binding; protein heterodimerization activity; protein homodimerization activity; RNA polymerase II cis-regulatory region sequence-specific DNA binding; sequence-specific DNA binding; sequence-specific double-stranded DNA binding; DNA binding; RNA polymerase II transcription regulatory region sequence-specific DNA binding
Biological process: fat cell differentiation; glucose metabolic process; negative regulation of apoptotic process; negative regulation of cell population proliferation; negative regulation of DNA-templated transcription; negative regulation of transcription by RNA polymerase II; positive regulation of cell population proliferation; positive regulation of DNA-templated transcription; positive regulation of neuron apoptotic process; positive regulation of transcription by RNA polymerase II; regulation of cell differentiation; regulation of insulin secretion; retina layer formation; aorta morphogenesis; collecting duct development; distal tubule development; ductus arteriosus closure; forelimb morphogenesis; hindlimb morphogenesis; kidney development; nervous system development; regulation of BMP signaling pathway; regulation of cell population proliferation; sympathetic nervous system development; gene expression; and 6 more
Cellular component: nucleus; chromatin; nucleoplasm
Genetic constraint (gnomAD): Loss-of-function variants: 9 observed, 44.51 expected, observed/expected ratio (o/e) 0.2, 90% interval 0.12 to 0.35. The upper end of that interval is the gene's LOEUF score, 0.35, which puts it in group 1 of 6, group 1 being the genes least tolerant of losing a copy. Missense variants: 509 observed, 620.51 expected, observed/expected ratio (o/e) 0.82, 90% interval 0.76 to 0.88. Synonymous variants: 270 observed, 276.03 expected, observed/expected ratio (o/e) 0.98, 90% interval 0.88 to 1.08.
Gene-disease validity (ClinGen):
ClinGen rates the evidence that TFAP2B causes each of these diseases.
TFAP2B-related congenital heart disease spectrum disorder (autosomal dominant): Definitive. Any congenital heart disease caused by pathogenic variation(s) in the TFAP2B gene, which encodes the transcription factor AP-2β.
Homologues: Orthologues: mouse Tfap2b (99% identical), pig TFAP2B (99% identical), chimpanzee TFAP2B (98% identical), dog TFAP2B (98% identical), rabbit TFAP2B (98% identical), rat Tfap2b (98% identical), tropical clawed frog tfap2b (95% identical), macaque TFAP2B (94% identical), zebrafish tfap2b (84% identical), guinea pig TFAP2B (66% identical), Drosophila melanogaster TfAP-2 (47% identical), Caenorhabditis elegans aptf-1 (31% identical), and 3 more. Paralogues in human: TFAP2A (71% identical), TFAP2E (63% identical), TFAP2C (59% identical), TFAP2D (52% identical).
Diseases named in the same sentence as TFAP2B in open-access papers:
TFAP2B is named in the same sentence as 89 diseases in open-access papers, as found by Europe PMC text mining. Sharing a sentence is not in itself a finding about the gene and the disease. The quoted sentences say what the papers report.
Obesity (29 papers, 2009 to 2025). Accumulation of substantial excess body fat. "Based on genome-wide association analysis data, genetic variants in FTO and TFAP2B, previously known as obesity susceptibility loci, impinge independently on the risk of metabolic syndrome." (PMID 36627697, 2023). "Studies from Asia have revealed that genetic predisposition to the FTO and TFAP2B genes contributed to a sex-dependent pattern of obesity-related traits and remarkable accumulation of abdominal fat." (PMID 36627697, 2023). "Only 11% of a participants had GG variant in TFAP2B gene, which in most studies was negatively associated with obesity." (PMID 34208363, 2021). "TFAP2B rs987237 is associated with obesity and has shown interaction with the dietary fat-to-carbohydrate ratio, affecting weight loss." (PMID 34208363, 2021). "KCTD15 is associated with TFAP2B, and both of them genes have been linked to obesity in GWASs, indicating a possible physical interaction in vivo." (PMID 31341224, 2019). "Two genes recently associated with obesity have been TFAP2B and KCTD15, for which a combined function that affects eating behavior has been described." (PMID 28948079, 2017). "Two loci significantly associated with obesity in Qataris: the TFAP2B variation (rs987237) (A allele versus G allele: chi-square = 10.3; P = 0.0013) and GNPDA2 variation (rs10938397) (A allele versus G allele: chi-square = 6.15; P = 0.013)." (PMID 25890290, 2015). "In the sex-stratified analysis, BMI and obesity were also nominally associated with a variant at the TFAP2B locus (beta ± SE: 1.22 ± 0.39, p = 0.002; OR = 1.96, 95% CI: 1.08–3.55, p = 0.026) in males." (PMID 23347264, 2013). "In the meta-analysis of 16 GWAS, the minor G-allele of rs987237 in TFAP2B associated significantly with central obesity measured by WC (p = 1.9×10−11) and general obesity measured by BMI (p = 7.0×10−12 (stage 2 alone)) in the mixed-gender analysis." (PMID 21674055, 2011). "Previously, TFAP2B has been investigated for associations with several phenotypes correlated to diabetes and obesity, and has been proposed to be a new gene for the metabolic syndrome." (PMID 21674055, 2011). "No heterogeneity between the study groups was observed for the investigated variants, except for TFAP2B rs987237 in the combined QT analysis in relation to general obesity (BMI) (Fixed effect, I2: 78%[41%–92%], p = 0.003)." (PMID 21674055, 2011). "The variants near TFAP2B appear to influence central adiposity through an effect on overall obesity/fat-mass, whereas LYPLAL1 displays a strong female-only association with fat distribution." (PMID 19557161, 2009). "The results of this study suggest that polymorphisms of the MC4R, PPARGC1A, MSRA, and TFAP2B genes may be associated with obesity-related traits in a sample of Portuguese children." (PMID 36499740, 2022). "In most studies, the TFAP2B (GG) genotype was negatively associated with obesity." (PMID 34208363, 2021). "We found four strains with lower metabolic rate that might predict obesity susceptibility, Pax5+/-, Chst8-/-, Tfap2b+/-, and Pald1-/-." (PMID 32356724, 2020). "The analysis of obese patients in our sample could confirm that KCTD15 and TFAP2B variants may be related to obesity risk, a finding that has also been suggested by a number of GWAS and replication studies." (PMID 28948079, 2017). "Furthermore, a recent study has also observed an association between TFAP2B SNPs and obesity‐related traits (Albuquerque, Nobrega, Rodriguez‐Lopez, & Manco, 2014)." (PMID 28948079, 2017). "The TFAP2B GG genotype negatively associated with obesity (OR = 0.21; P = 0.0031)." (PMID 25890290, 2015). "Our study describes how the obesity-linked homologues TfAP-2 (human TFAP2B) and Tiwaz (human KCTD15) regulate a unique feedback system involving noradrenalin-like octopamine and the CCK homolog Dsk, that exert positive and negative effects on Drosophila feeding behavior." (PMID 25187989, 2014).
Obesity (continued). "In conclusion, our data suggests that the human obesity-linked genes TFAP2B and KCTD15 could directly interact in regions of the brain known to regulate feeding behavior." (PMID 25187989, 2014). "However, TFAP2B was confirmed as an obesity locus in the recent meta-analysis, where this variant associated with BMI at a genome-wide significant level." (PMID 21674055, 2011). "Interestingly, another member of the AP-2 family (TFAP2B) has been widely studied for its association with obesity and BMI variability, reinforcing that the AP-2 family has a crucial role to play in the development of obesity." (PMID 33003475, 2020). "Previous GWASs have demonstrated the association of the studied polymorphic loci ADCY3 rs1167627272, CLOCK rs1801260, FTO rs1421085, GPR61 rs41279738, RP11-775H9.2 rs1296328, SLC22A3 rs9364554, and TFAP2B rs734597 with obesity-related phenotypes." (PMID 39766774, 2024). "We identified obesity association for 6 SNPs near SEC16B, RBJ, CDKAL1, TFAP2B, MAP2K5 and FTO (odds ratios (ORs) ranged from 1.19 to 1.41, nominal two-sided P-values < 0.05)." (PMID 26800887, 2016). "We identified the nominally significant associations with obesity for effect alleles of 6 SNPs at FTO, SEC16B, TFAP2B, RBJ, MAP2K5 and CDKAL1 (ORs for the effect allele ranged between 1.19 and 1.41, nominal two-sided P < 0.05)." (PMID 26800887, 2016). "Further, Tfap2b was also affected by the high-fat diet with up-regulated relative expression levels at 4.78 (SD ±0.67, P>0.01), while Kctd15 was unaffected by obesity (0.99±0.09 (±SD)." (PMID 25187989, 2014). "The first model included genetic variants known to be associated with obesity—specifically, ADCY3 rs11676272, CLOCK rs1801260, GPR61 rs41279738, FTO rs1421085, RP11-775H9.2 rs1296328, SLC22A3 rs9364554, and TFAP2B rs734597—and explained 8.3% of the variance in BMI." (PMID 39766774, 2024). "rs987237 located in the chromosome 6 transcription factor AP-2 beta gene (TFAP2B) has been related to obesity defined by body mass index (BMI), and waist circumference, and has been shown interaction with the dietary fat-to-carbohydrate ratio, which has an impact on weight loss." (PMID 35694671, 2022). "The transcription factor encoded by TFAP2B is mainly expressed in adipose tissue, where its regulation of adipocyte function and expression of adipokine is considered to be the functional link to obesity, to provide a mechanistic basis for the genetic correlation of TFAP2B and obesity." (PMID 35694671, 2022). "Strains with lower metabolic rate which might contribute to development of obesity include Chst8, Pax5, Pald1, and Tfap2b." (PMID 32356724, 2020). "However, analyses were made without adjusting for multiple testing, and further studies are needed to elucidate the involvement of LYPLAL1, NRXN3, MSRA, and TFAP2B in the pathophysiology of obesity." (PMID 21674055, 2011). "However, analyses were made without adjusting for multiple testing, and further studies are needed to confirm the putative role of LYPLAL1, NRXN3, MSRA, and TFAP2B in the pathophysiology of obesity." (PMID 21674055, 2011). "We showed an association between central obesity and rs987237 TFAP2B minor G-allele, however, we were not able to determine the underlying phenotype for this association in the quantitative trait analysis of obesity-related measures, nor did we show any association with type 2 diabetes." (PMID 21674055, 2011). "For obesity, TMEM18 and TFAP2B were identified here for the first time as loci for BMI or weight change." (PMID 39609904, 2024). "For each participant, three SNPs in three genes (FTO rs9939609, TFAP2B rs987237, PLIN1 rs894160) related to obesity were genotyped." (PMID 36142109, 2022). "In this study, we respectively constructed specific miRNA-mRNA regulatory networks of obesity-related ccRCC for both VAT and SAT, and 3 RNA pairs (i.e. hsa-miR-182&ATP2B2, hsa-miR-532&CDH2 in VAT; and hsa-miR-425&TFAP2B in SAT) were finally screened out." (PMID 34621242, 2021).
Obesity (continued). "These SNPs were located mainly in genes related to atherosclerosis and obesity such as FADS2 (rs174577 and rs174589), GATA 2 (rs3803) and TFAP2B (rs2272903)." (PMID 27589269, 2016). "Examples of genome-wide significant age-associated sites include CpG loci located in the promoter region of the obesity gene LEP, the childhood obesity gene OLFM4, the T2D gene IRS2, and the newly identified MetS gene TFAP2B." (PMID 25806089, 2015). "TFAP2B and KCTD15 are obesity‐related genes that interact to regulate feeding behavior." (PMID 28948079, 2017).
Char syndrome (23 papers, 2009 to 2024). Char syndrome is characterized by the triad of patent ductus arteriosus (PDA), facial dysmorphism and hand anomalies. "The top upregulated target is TFAP2B, which, upon mutation, can cause Char syndrome, characterized by facial, ductal, and hand anomalies." (PMID 36782060, 2023). "With respect to humans, TFAP2A mutations are associated with Branchio-Oculo-Facial Syndrome (MIM, 113620), while TFAP2B is mutated in Char Syndrome (MIM, 169100)." (PMID 35333176, 2022). "For both the Char syndrome variants, protein levels of TFAP2B were still detectable and comparable to the wild type, which is in line with the suspected dominant negative effect previously reported for missense variants associated with this syndrome." (PMID 35874825, 2022). "In humans, germline mutations of TFAP2B cause Char syndrome, an autosomal dominant disorder characterized by patent ductus arteriosis, digital abnormalities and facial dysmorphism." (PMID 36710876, 2022). "It has been known that mutations in tfap2b cause Char syndrome, a familial form of patent ductus arteriosus in humans and that mutations or deficiency in tfap2b cause patent ductus arteriosus in mice." (PMID 30897181, 2019). "In mice, TFAP2B deletion has been demonstrated to cause congenital polycystic kidney disease, and several point mutations in the TFAP2B coding region are associated with Char syndrome, a human autosomal dominant disorder." (PMID 31113934, 2019). "It has been reported that mutations in TFAP2B cause Char syndrome, which is characterized by facial dysmorphism, patent ductus arteriosus, and finger anomalies." (PMID 29113774, 2017). "Mutations in TFAP2B cause Char syndrome, a disorder characterized by defective heart, craniofacial and limb development." (PMID 28707729, 2017). "Char Syndrome, a congenital disease characterized by patent ductus arteriosus and facial and hand anomalies, was linked to mutations in TF AP-2-beta (TFAP2B)." (PMID 27176626, 2016). "Isolated PDA has also been linked to mutations in TFAP2B and a recent Tfap2B knock out study in mice reported phenotypes resembling the characteristics of Char syndrome." (PMID 23934094, 2014). "Mutations in transcription factor TFAP2B cause Char syndrome, a human disorder characterized by PDA, facial dysmorphysm and hand anomalies." (PMID 21829553, 2011). "Char syndrome is linked to the chromosome 6p12–p21 and missense mutations are identified in the TFAP2B gene in unrelated families with genotype-phenotype correlations." (PMID 21829553, 2011). "In a later study, splice site mutations within the TFAP2B gene have been identified causing Char syndrome in a haploinsufficiency mechanism." (PMID 21829553, 2011). "Further studies have shown that Char syndrome is caused by defects in TFAP2B, encoding a neural crest-related transcription factor (also known as AP-2β)." (PMID 19591690, 2009). "Importantly, mutations in human TFAP2A and TFAP2B, are also linked to the human conditions Branchio-Oculo-Facial Syndrome and Char Syndrome respectively, conditions which both have a craniofacial component." (PMID 35333176, 2022). "Moreover, TFAP2B loss of function variants have been linked to Char syndrome with variable expressivity of PDA, familial and non-familial isolated PDA and syndromic craniosynostosis." (PMID 35874825, 2022). "However, while the majority of Char syndrome patients carry an autosomal dominant heterozygous missense variant in TFAP2B, nonsense, splice site, and missense variants have been identified in syndromic craniosynostosis." (PMID 35874825, 2022). "It has been suggested that mutation TFAP2B causes Char syndrome, which is a familial form of PDA." (PMID 25806788, 2015). "Interestingly, mutations in TFAP2B causes Char syndrome (OMIM #169100) characterized by facial dysmorphism, anomalies of the fifth finger and patent ductus arteriosus (PDA)." (PMID 23934094, 2014).